IL17C (interleukin 17C)
Diseases named in the same sentence as IL17C in open-access papers (continued):
Sharing a sentence is not in itself a finding about the gene and the disease.
tumor (30 papers, 2018 to 2025). "The increase in IL-17C caused by commensal bacteria would induce the expression of B-cell lymphoma-2 and Bcl-xL in intestinal epithelial cells, leading to tumor cell survival and tumorigenesis." (PMID 37190326, 2023). "Remarkably, the numbers of neutrophils were twice as high in the tumor lesions compared to the parenchyma and significantly decreased in mice deficient for IL-17C." (PMID 31316109, 2019). "Furthermore, we identified a significant increase in interleukins and tumour necrosis factors, including IL‐1a, IL‐1b, IL‐6, IL‐17C, IL‐32, IL‐36G and TNF, along with its associated enzyme." (PMID 39865778, 2025). "Thus, the decreased expression of tumor-promoting cytokines may be one factor responsible for the decreased tumor-proliferation in Il-17c deficient mice." (PMID 31316109, 2019). "Together, our data suggest that COPD-like inflammation associates with a tumor microenvironment that is required for an efficient anti-PD-1 therapy, but, at the same time, also promotes the expression of innate cytokines, such as IL-17C, that counteract the response to immune checkpoint inhibitors." (PMID 31316109, 2019). "Consistent with the in vitro results, treatment with 100 ng/ml of IL-17C significantly reduced the tumour size of UH-SCC-17B by approximately 10 %." (PMID 40974979, 2025). "For instance, in non-small cell lung cancer, IL-17C promotes tumour growth by mediating neutrophil recruitment." (PMID 40974979, 2025). "Consistent with our in vitro findings, the zebrafish xenograft assay demonstrated that IL-17C significantly reduced tumour size by approximately 10 %, mirroring the effect observed in vitro." (PMID 40974979, 2025). "IL-17C is a 15–20-kDa glycosylated cytokine that plays a crucial role in mucosal immunity, with potential pro-tumour or antitumour effects." (PMID 40974979, 2025). "We obtained HGSOC patient tumor tissues and confirmed the elevated expression of IL-17A and IL-17C via reverse transcriptase polymerase chain reaction (qRT-PCR) compared with normal FTE tissues from patients with benign gynecological diseases." (PMID 38255960, 2024). "Another poor prognostic factor in our model, IL17C, has been shown to promote tumor growth in NSCLC xenograft models after its upregulation by proline dehydrogenase." (PMID 37434467, 2023). "IL17C and TNFSF15 are involved in tumorigenesis and development by impacting immune cell function, and MIA is associated with tumor invasion." (PMID 36936375, 2023). "Using both animal models and patient lung cancer samples, it was found that Haemophilus influenzae induced IL-17C expression, which promoted neutrophilic inflammation in the tumor microenvironment." (PMID 36838253, 2023). "In APCmin/+ mice and a colitis-associated cancer mouse model, commensal E. coli increases the IL-17C expression, promoting tumor cell proliferation by suppressing apoptosis, inducing BCLXL, and recruiting tumor-promoting lymphocytes." (PMID 35625485, 2022). "IL-17C has been shown to promote tumor progression by increasing epithelial cell survival and tumor angiogenesis in CRC." (PMID 35574420, 2022). "In conclusion, we have identified that IL-17C promotes tumor angiogenesis in CRC by activating intestinal epithelial and endothelial cells in an autocrine and paracrine manner." (PMID 32492770, 2020). "Given that this increased migration activity was suppressed by the VEGFR2 inhibitor Ki8751 pretreatment, we are convinced that VEGF is the key molecule in epithelial and endothelial cell communication during IL-17C signaling in tumor angiogenesis." (PMID 32492770, 2020). "Taken together, our study demonstrates that IL-17C promotes tumor angiogenesis through VEGF production via a STAT3/miR-23a-3p/SEMA6D axis, suggesting its potential as a novel target for anti-CRC therapy." (PMID 32492770, 2020). "IL-17C-treated tumors grew bigger and faster, compared with than vehicle-treated tumors, resulting in substantially increased tumor volumes." (PMID 32492770, 2020).
tumor (continued). "Alteration in gut microbiota can trigger IL-17C upregulation, which promotes tumor progression by increasing IEC survival in an autocrine manner." (PMID 32492770, 2020). "IL-17C has been demonstrated to exhibit tumor enhancing activity by increasing epithelial cell survival in CRC." (PMID 32492770, 2020). "While IL-17D and IL-17E appear to exert preponderant tumor-protective activities, IL-17B, IL-17C, and IL-17F are tumor promoting, either through a direct effect on tumor cells, or by modulating the tumor microenvironment." (PMID 33244315, 2020). "In vitro and ex vivo angiogenesis, a mouse xenograft experiment, and immunostaining were performed to test the effect of IL-17C on tumor angiogenesis." (PMID 32492770, 2020). "In the present work, we showed a specific molecular mechanism by which IL-17C regulates tumor angiogenesis in CRC." (PMID 32492770, 2020). "IL-17C-induced VEGF production was found to be closely related to STAT3 signaling pathway that promotes tumor growth." (PMID 32492770, 2020). "Because human VEGF can induce angiogenesis in other species, IL-17C-induced increase of human VEGF effectively promoted tumor angiogenesis by using and recruiting mouse endothelial cells without mouse VEGF expression in the mouse xenograft model." (PMID 32492770, 2020). "A cytokine IL17C (inflammatory response signaling) produced by lymphocyte subsets of Th17 cells is involved in the pathogenesis of chronic inflammatory responses and could induce the expression of vascular endothelial growth factor that could then induce TGFβ to cause tumor growth and metastasis." (PMID 31126066, 2019). "Ki-67 staining showed that NTHi-induced inflammation of the lung resulted in an increased tumor cell proliferation in an IL-17C-dependent manner." (PMID 31316109, 2019). "Research by Jungnickel shows that IL-17C promotes neutrophilic inflammation in the tumor microenvironment and suggests that IL-17C links a pathologic microbiota, with enhanced tumor growth." (PMID 31803158, 2019). "IHC staining showed that the numbers of tumor associated PD-1+ cells as well as CD4+ and CD8+ cells were significantly increased after exposure to NTHi for four weeks in an IL-17C-independent manner." (PMID 31316109, 2019). "Here, we demonstrate that the pro-inflammatory cytokine IL-17C promotes the rapid recruitment of neutrophils into the tumor microenvironment, the expression of tumor-promoting-cytokines, and tumor proliferation in the presence of COPD-like lung inflammation." (PMID 31316109, 2019). "We provide evidence that ablation of IL-17C decreases inflammation-induced tumor growth and enhances the response to anti-PD-1 antibody treatment." (PMID 31316109, 2019). "This suggests that IL-17C mediates the expression of tumor-promoting cytokines through the activation of MAP kinase signaling pathways." (PMID 31316109, 2019). "Taken together, our data suggest that IL-17C promotes proliferation of tumor cells through the regulation of innate immune mechanisms in the tumor microenvironment." (PMID 31316109, 2019). "Moreover, IL-17C reduced the tumour size of UH-SCC-17B cells by approximately 10% in the zebrafish model." (PMID 40974979, 2025). "•IL-17C suppressed OSCC tumour growth both in vitro and in vivo." (PMID 40974979, 2025). "In this study, we demonstrated that IL-17C regressed OSCC tumour growth both in vitro and in vivo." (PMID 40974979, 2025). "The neutrophilic inflammation driven by IL-17C resulted in enhanced tumor growth." (PMID 36838253, 2023). "IL-17A, IL-17B, IL-17C, as well as IL-17F have been shown to promote tumor development, whereas IL-17D and IL-17E play anti-cancer roles in a context-dependent manner by activating the Nrf2 stress surveillance pathway, recruiting innate immune cells, and activating leukocytes." (PMID 36140808, 2022). "Moreover, histological analysis of IL-17C-treated xenografts showed increased tumor vascularity, while Ki8751 co-treatment suppressed the angiogenic effect of IL-17C." (PMID 32492770, 2020).
tumor (continued). "Accordingly, the primary objectives of this study include 1) to determine whether IL-17C plays a role in tumor angiogenesis and progression of CRC; 2) to uncover whether miRNAs are involved in IL-17C signaling, thereby regulate pro-angiogenic VEGF production." (PMID 32492770, 2020). "Our data indicated that IL-17C promoted tumor angiogenesis in CRC." (PMID 32492770, 2020). "Moreover, IL-17C markedly accelerated xenograft tumor growth, which was manifested by substantially reduced tumor growth when treated with the VEGF receptor 2 inhibitor Ki8751." (PMID 32492770, 2020). "Furthermore, the levels of secreted human VEGF were increased by IL-17C injection in tumor tissues, indicating that IL-17C can also promote tumor progression in in vivo mouse xenograft models through IL-17C-stimulated human VEGF production in DLD-1 cells." (PMID 32492770, 2020). "Thus, in monitoring tumor growth in the presence of Ki8751, we found that co-treatment with Ki8751 suppressed IL-17C-induced tumor growth." (PMID 32492770, 2020). "Therefore, we aimed to investigate the effect of IL-17C on tumor angiogenesis, the involvement of miR-23a-3p in IL-17C signaling, and the direct target gene of miR-23a-3p in CRC." (PMID 32492770, 2020). "We therefore explored whether IL-17C-mediated activation of innate immune responses affects Kras-driven tumor growth in a model of chronic COPD-like inflammation." (PMID 31316109, 2019). "Therefore, we propose a disease model, in which activation of innate immune mechanisms through IL-17C promotes the recruitment of myeloid cells, such as neutrophils, into the tumor microenvironment." (PMID 31316109, 2019). "Moreover, the expression of the tumor-promoting cytokines IL-6, which has been shown to be regulated by IL-17C in different disease models, and CCL5 was decreased in lungs of IL-17C deficient Kras mice." (PMID 31316109, 2019). "Therefore, IL-17C-mediated expression of tumor-promoting cytokines (e.g. IL-6) seems to decrease the sensitivity to PD-1 blockade." (PMID 31316109, 2019). "Tumor growth was decreased in Il-17c deficient mice but not in wildtype mice after anti-PD-1 treatment." (PMID 31316109, 2019). "Interleukin-17C has been shown to be tumor-promoting in OC cell models." (PMID 30519148, 2018). "In our results, it is confirmed that the expression of IL-17A, IL-17B, IL-17C, IL-17D, IL-17E (IL-25), and IL-17F in tumor immune subtypes is statistically significant, especially in BRCA; there may be a potential microenvironmental regulation mechanism that remains to be investigated." (PMID 36159856, 2022). "Given that cell-cell interaction between cancer and endothelial cells is crucial for tumor angiogenesis, we investigated whether cancer cell-derived factors could affect angiogenesis in endothelial cells and thus IL-17C stimulation modulates the secretion of those factors by DLD-1 cells." (PMID 32492770, 2020). "It was found that IL17C is higher expressed in CRC tissue and induces tumor angiogenesis of intestinal endothelial cells via VEGFR2 production, subsequently enhancing cell invasion and migration of CRC cells." (PMID 37228491, 2023). "Three hub genes (IL17C, TNFSF15, and MIA) related to tumor immunity and metastasis were identified by WGCNA, and the abnormal expression of each hub gene in ESCA has a poor prognosis, especially in patients with high expression (P < 0.05)." (PMID 36936375, 2023). "The expressions of IL17C, TNFSF15, and MIA in tumor tissues were significantly different from those in adjacent tissues." (PMID 36936375, 2023). "On this basis, IL17C, TNFSF15, and MIA which were related to tumor immunity, invasion, and metastasis were identified." (PMID 36936375, 2023). "To delineate the role of upregulated VEGF production in tumorigenesis of IL-17C-treated xenografts, we used the VEGFR2 inhibitor Ki8751 (10 μg/tumor, peritumoral injection) to block the biological activity of VEGF." (PMID 32492770, 2020).
tumor (continued). "We found that increased IL-17C-induced miR-23a-3p expression can suppress anti-angiogenic activity of SEMA6D and increase VEGF induction to promote tumor growth and tumor angiogenesis." (PMID 32492770, 2020). "Having found the critical role of VEGF in IL-17C-induced angiogenesis, we sought for the possibility that IL-17C-induced VEGF of epithelial origin can affect endothelial cells in the tumor microenvironment." (PMID 32492770, 2020). "A prognostic signature based on RGs (AGTR1, CTGF, FAM3B, IL11, IL17C, PTH2R and SPAG11A) performed moderately in prognostic predictions and correlated with age, tumor stage, metastasis, number of lesions, and tumor burden." (PMID 30661062, 2019). "The IL-17C expression was nearly absent across all major cell types in both primary and metastatic tumour samples." (PMID 40974979, 2025). "Therefore, exploring the role of IL-17C in CRC progression and its possible function in tumor angiogenesis expands our understanding of CRC development." (PMID 32492770, 2020). "We also demonstrate that treatment with a PD-1-blocking antibody decreases inflammation in the tumor microenvironment and reduces tumor growth in the absence of IL-17C." (PMID 31316109, 2019). "We found that chronic COPD-like inflammation results in the expression of PD-1 and PD-L1 in immune cells in the tumor microenvironment independent of IL-17C." (PMID 31316109, 2019). "Similarly, hsa-miR-23a-3p seems to enhance tumor and vascular growth in CRC via the Signal Transducer and Activator of Transcription 3/miR-23a-3p/Semaphorin 6D (STAT3/miR-23a-3p/SEMA6D) axis induced by Interleukin-17C (IL-17C), which also leads to VEGF production." (PMID 37444431, 2023).
cancer (14 papers, 2018 to 2025). A tumor composed of atypical neoplastic, often pleomorphic cells that invade other tissues. "C-Myc has been shown to act as a transcription factor that induces the transcription of genes encoding cytokines, including IL-2, IL-13 and IL-17C, in cancer cells." (PMID 35954273, 2022). "In the forest plot, we found that IL-17B and IL-17C had important prognostic significance with hazard ratio (HR) >1 in the majority of cancers, which was recognized as a high-risk prognostic factor." (PMID 36159856, 2022). "Among the lesser-studied members of the IL-17 family, IL-17C remains one of the least explored, with its role in cancer progression is poorly understood." (PMID 40974979, 2025). "To further understand the signalling pathways involved in the IL-17C-mediated inhibition of cancer cell proliferation, we performed GSEA." (PMID 40974979, 2025). "As for IL-17A, the role of IL-17B, IL-17C, IL-17D, IL-17E, and IL-17F in cancer remain controversial." (PMID 33244315, 2020). "Functionally, the IL-17C/RE axis has been described to be involved in the pathogenesis of several diseases ranging from infectious and autoimmune conditions to cancer development and progression." (PMID 32174926, 2020). "Western blot analysis revealed increased levels of p-ERK in lysates of the cancer cell lines after 30 and 60 minutes of incubation with IL-17C and the combination of NTHi." (PMID 31316109, 2019). "As demonstrated for colonic epithelial cells we show in this study that IL-17C induces the rapid phosphorylation of ERK in cultured cancer cell lines and HBECs." (PMID 31316109, 2019). "With regards to cancer, IL-17C is upregulated in several forms of cancer, including colorectal and lung cancer, and was consistently shown to contribute to enhanced tumorigenesis in mice models." (PMID 30127781, 2018). "Our data revealed that IL-17C is minimally expressed in HNSCC; however, both of its receptors are expressed at varying levels in HNSCC cancer cells, suggesting that these cells could serve as suitable targets for IL-17C stimulation." (PMID 40974979, 2025). "Recent studies suggest that IL-17C may have both pro- and antitumorigenic functions, depending upon cancer type." (PMID 40974979, 2025). "IL-17C is hypothesized to contribute to the pathogenesis of several infectious diseases as well as cancer." (PMID 38590952, 2024). "Additionally, IL-17C expression increased in DLD-1 cancer cells, compared with NCM460 normal epithelial cells." (PMID 32492770, 2020). "The IL-17 family of cytokines is composed of six members named IL-17A (commonly known as IL-17), IL-17B, IL-17C, IL-17D, IL-17E (also known as IL-25), and IL-17F with different sequence homology and functions that are important players in host defense responses, inflammation, and cancer development." (PMID 38068860, 2023). "Thus, either blocking the IL-17C/IL-17RE axis or acting on the gut microbiome might be beneficial to cancer patients." (PMID 33244315, 2020). "Unexpectedly, IL-17C also enriched the MYC gene set, a well-known driver of cancer progression frequently overexpressed in HNSCC." (PMID 40974979, 2025). "IL-17C, another member of IL-17 family synthesized by epithelial cells, initiates an autocrine loop within epithelial tissues, which consequently upregulates IL-17A expression in TH17 cells and promotes cancer cell proliferation." (PMID 38255960, 2024). "Moreover, elevated levels of serum and tissue IL17C were observed in patients with active IBD, which can result in cancer progression." (PMID 37228491, 2023). "IL-17C further increased DLD-1 cell malignancy by increasing their invasiveness and migration activity, rather than promoting cancer cell proliferation and survival." (PMID 32492770, 2020).
bacterial infection (9 papers, 2013 to 2025). "IL-17C is functionally unique from the rest of the members of the IL-17 family because it is induced by various stimulations, such as bacterial infection and cytokine treatment." (PMID 33162788, 2020). "Similar to IL-17A and IL-17F, IL-17C also seems to mediate inflammatory processes and has been detected in lung and skin tissues after bacterial infection as well as in the colon of inflammatory bowel disease patients." (PMID 31221216, 2019). "The upregulated genes included genes encoding innate immunity effectors, such as IL-17C, CCL20, and TNF, which contribute to combat bacterial infections." (PMID 26485688, 2015). "Previous studies have shown IL-17A/F, IL-17B, IL-17C, IL-17D and IL-17N could stimulate the expression of proinflammatory cytokines, chemokines and antimicrobial peptides in response to bacterial infection." (PMID 40149405, 2025). "This prompted us to explore the possibility that bacterial infection may regulate IL-17C secretion in adenoids." (PMID 33162788, 2020). "Considering ETEC infection can induce the production of IL-17C, we speculate that IL-17C might participate in the regulation of the integrity of the intestinal barrier at a later stage of the bacterial infection." (PMID 31221216, 2019). "Bacterial infection or stimulation with PAMPs activates the TLR signaling pathway, which is important in the initiation of innate immunity, suggesting that IL-17C may be important to innate immunity." (PMID 33162788, 2020). "Moreover, this “early” feature of IL-17C that we found is not surprising, as it is expressed by epithelial cells during bacterial infections at earlier timepoints in disease than IL-17A." (PMID 38407673, 2024).